CCND2 (cyclin D2)
Diseases named in the same sentence as CCND2 in open-access papers (continued):
Sharing a sentence is not in itself a finding about the gene and the disease.
glioma (32 papers, 2008 to 2025). A benign or malignant brain and spinal cord tumor that arises from glial cells (astrocytes, oligodendrocytes, ependymal cells). "CCND2 (Cyclin D2) may reflect a more differentiated cellular state in glioma, consistent with its favorable prognostic association." (PMID 41356219, 2025). "CCND2 and its encoded cyclin D2 protein both regulate the cellular progression of glioma cells." (PMID 30973678, 2019). "Moreover, the up‐regulation of LINC00511 competitively sponges the miR‐124‐3p, thereby motivating the CCND2 and its encoded cyclin D2 protein expression, which might likely provide great promise for glioma therapeutics." (PMID 30973678, 2019). "Conversely, the protective associations observed with PTK2, CCND2, RAD51L3-RFFL, and MAX suggest potential compensatory or tumor-suppressive functions in glioma." (PMID 41356219, 2025). "CircHIPK3 elevates CCND2 expression and promotes cell proliferation and invasion in gliomas via miR-124." (PMID 36254231, 2022). "STAT3 enhanced the transcription of apoptosis regulator Mcl-1 and cell cycle regulator cyclin D2 (CCND2) to decrease the sensitivity of cancer cells to radiation, according to more research on the glioma, as well as colorectal cancer." (PMID 36231093, 2022). "RPTOR amplification was found to be significantly associated with young adult BRCA (FDR = 0.020), while amplifications of KDM5A, CCND2, KRAS, and ARRDC1 were each suggestively associated with young adult gliomas (FDR ≤ 0.148)." (PMID 34788626, 2021). "We also investigated the potential mechanisms and found that miR-124 regulated glioma through the regulation of CCND2." (PMID 33005182, 2020). "In this study, we found that CCND2 expression was increased in gliomas and was a direct target of miR-124." (PMID 33005182, 2020). "In summary, our results indicated that circHIPK3 had carcinogenic effects by regulating the expression of CCND2 in glioma by sponging miR-124." (PMID 33005182, 2020). "The TCGA data analysis showed that CCND2 was upregulation in glioma samples compared to normal tissues." (PMID 33005182, 2020). "Overall, our finding illuminates that LINC00511 is induced by SP1 and accelerates the glioma progression through targeting miR‐124‐3p/CCND2 axis, constructing the SP1/LINC00511/miR‐124‐3p/CCND2 axis." (PMID 30973678, 2019). "The data based on the TCGA demonstrated that the CCND2 level was noticeably overexpressed in the glioma tissue samples." (PMID 30973678, 2019). "The correlation between the expression levels of these miR-206 and cyclin D2 is therefore likely to be important in the development of gliomas." (PMID 25572712, 2015). "All in all, the roles of miR-124 and CCND2 in glioma still keep unclear." (PMID 33005182, 2020). "In glioma, CCND2 AS1 promotes proliferation and growth via effects on Wnt/β-catenin signaling." (PMID 32607313, 2020). "Genetic aberrations of CCND2 are also frequently described in gliomas and hematologic malignancies." (PMID 28382019, 2017). "CCND2 is amplified in 2% of gliomas and in zebrafish and human MPNSTs." (PMID 24009521, 2013). "Moreover, CCND2 is a cyclin expressed mainly in glioma stem cells." (PMID 33198677, 2020). "Cyclin D1 (CCND1) and Cyclin D2 (CCND2) are key regulators of cell proliferation in various cell types, including glioma cells, placental trophoblast cells, and granulosa cells." (PMID 41460875, 2025). "Western blot analysis and IHC showed that cyclin D1, cyclin D2, CDK4, CDK6, Ki-67, Bcl-2 and Bax were involved in the NRXN3-induced inhibitory effect on glioma growth." (PMID 34035217, 2021). "In young adult gliomas, we identified enrichment of KRAS and CCND2 amplifications with potential targeted treatment options, whereas later-onset LGG showed higher rates of actionable EGFR amplification." (PMID 34788626, 2021).
glioma (continued). "HIF1α activates target gene expression involved in vascularization, glucose transport, energy metabolism, and growth and metastasis, including VEGF, PDK1, Cyclin-D2, and CA9, and makes glioma cells adapt to hypoxic environments." (PMID 30082910, 2019). "LINC00511 enhance the tumourous phenotype via sponging the miR‐124‐3p and targeting CCND2 production, thereby providing a model for LINC00511‐mediated cellular regulation in glioma." (PMID 30973678, 2019). "It was reported that development of a high-grade glioma phenotype was associated with temozolomide-driven hypermutation and acquired alterations of the cell cycle regulators CDKN2A and CCND2, which have been shown to occur exclusively in post-radiation IDH—mutant gliomas." (PMID 39684714, 2024). "Particularly, MYC, CCND2, and ARID1B were regulated by more than six enhancers in gliomas." (PMID 33537074, 2021). "Moreover, it has been also demonstrated that glioma tumorigenesis and malignancy were facilitated by upregulated FOXD2-AS1 through downregulating miR-185-5p and increasing CCND2 expression." (PMID 31770107, 2019). "There are reports which imply a special relationship between WNT/beta catenin signaling and CCND2 in glioma cells but not in smooth muscle cells." (PMID 29881541, 2018). "Notably, basal cyclin D1 levels were higher in CD133+ cells than matched CD133− cells, whereas cyclin D2 and cyclin E levels were higher in CD133− cells, suggesting that cyclin D1, but not cyclins D2 or E, is critical for the G1/S transition in CD133+ glioma cells." (PMID 19020659, 2008).
myeloma (30 papers, 2012 to 2025). "In fact, the shortening of CCND2 3′UTR by alternative polyadenylation with the consequent loss of miRNA binding sites was demonstrated both in myeloma cell lines and primary myeloma samples." (PMID 30654527, 2019). "Moreover, rapamycin sensitized multiple myeloma cell lines to dexamethasone-induced apoptosis, associated with decreased expression of cyclin D2 and survivin." (PMID 23638184, 2013). "Together, this evidence reveals a central mechanism by which ZKSCAN3 drives multiple myeloma progression through transcriptional regulation of the CCND2-VEGF signaling axis." (PMID 40723888, 2025). "Overexpression of ZKSCAN3 enhances CCND2 promoter activity and induces protein expression, whereas gene silencing significantly reduces CCND2 levels, which in turn inhibits myeloma cell proliferation." (PMID 40723888, 2025). "Utx/BrafV600E plasma cells before and after overt MM showed gradual up-regulation and down-regulation of DEGs, including representative myeloma signature genes with upregulation of Myc, Ccnd2, E2f3, and Irf4 and downregulation of Cd19 and Ikzf3." (PMID 37198323, 2023). "In a complementary approach, we employed KRAB-dCAS9 CRISPRi in MAF-translocated myeloma cells to repress the activity of four prominent constituent peaks 1–4 which engage in high-frequency interactions with the CCND2 promoter." (PMID 34521827, 2021). "Through this process we discover cis- and trans-regulators of myeloma biology, including those involved in the regulation and aberrant expression of CCND2 in MM." (PMID 34521827, 2021). "In the case of CCND2, ‘recommissioning’ entails activation in myeloma PC of Polycomb-imposed ‘poised’ transcriptional states in GCB cells and normal PC." (PMID 34521827, 2021). "CLL malignant B cells express significantly higher CCND2 than CCND1 levels and as in CCND2high myeloma PC, we found that the same CCND2 super-enhancer is active in CLL B cells." (PMID 34521827, 2021). "Despite extensive genetic heterogeneity, nearly half of all multiple myeloma (MM) cases are driven by cyclin D2 (CCND2) over-expression." (PMID 34521827, 2021). "They found that SEs assist the high level transcription of genes [e.g., MYC, IRF4 (interferon regulatory factor 4), XBP1 (X-box binding protein 1), CCND2 (Cyclin D2)] that are deregulated in multiple myeloma cells." (PMID 31824865, 2019). "Previous reports showed that A77 1726 induced G1 cell cycle arrest via modulation of cyclin D2 and pRb expression in myeloma cells." (PMID 29348830, 2017). "Gene expression profiling of B cells from M-protein-positive p80HT mice revealed aberrant expression of genes known to be important in the pathogenesis of multiple myeloma, including cyclin D1, cyclin D2, Blimp1, survivin, IL-10 and IL-15." (PMID 22642622, 2012). "Myeloma cells treated with 50 μM etomoxir exhibited a significant but modest reduction in the protein levels of cyclin D2 and CDK6." (PMID 23029529, 2012). "A suppression of the expression of CCND2 using RNA interference (a method similar to miRNA inhibition) in myeloma cells inhibited proliferation and was progressively cytotoxic." (PMID 22253745, 2012). "Moreover, ZKSCAN3 engages with the promoter region of cyclin D2 (CCND2) in multiple myeloma, leading to its upregulated expression compared to normal samples." (PMID 39519085, 2024). "ZKSCAN3 selectively binds to CCND2 promoter sequences in myeloma cells." (PMID 39519085, 2024). "In addition to translocation and myeloma subgroups, we found novel active domains, for instance, proximal to CCND2 and TRMT9B in MMSET patients." (PMID 33138842, 2020). "Likewise, myeloma cells treated with 20 μM orlistat exhibited a significant reduction in p21 and phospho-pRb levels in myeloma cells, whereas cyclin D1, cyclin D2, cyclin E, CDK4, CDK6, p16 and p27 remained unchanged." (PMID 23029529, 2012).
myeloma (continued). "Examples include TRA::MTCP1 for T-PLL, TYK2 rearrangement for T-cell lymphomas; CCND1 and CCND2 rearrangement with IGK and IGL in mantle cell lymphoma; MYC rearrangements and hyperdiploidy in multiple myeloma." (PMID 40361363, 2025). "ZKSCAN3 interacts with the CCND2 and VEGF promoters, activating their expression in multiple myeloma." (PMID 39519085, 2024). "ZKSCAN3 was also shown to interact with the cyclin D2 (CCND2) promoter and activate its expression in multiple myeloma, in which ZKSCAN3 is also highly expressed compared to normal samples." (PMID 33672287, 2021). "One of the striking features of myeloma biology is the early observation that a dichotomous over-expression of the cell cycle regulators CCND1 and CCND2 overarches genetic diversification." (PMID 34521827, 2021). "We discovered that 5hmC strongly persists at key oncogenic genes such as CCND1, CCND2 and MMSET and characterized domains that are specifically hydroxymethylated in myeloma subgroups." (PMID 33138842, 2020). "We validated this correlation between gain(1q)-HRD and CCND2 and gain(11q25)-HRD and CCND1 expression in the Myeloma IX dataset." (PMID 28584253, 2018). "These downstream genes mainly include cyclin D2, integrin β7, CCR1, and ARK5, which are responsible for cell cycle progress, bone marrow stromal cell adhesion, MM cell proliferation, and myeloma cell invasion, respectively." (PMID 28673317, 2017). "For example, in multiple myeloma cells, APRIL promotes cell cycle progression in cyclin D2-positive cells by upregulating CDK4, CDK6, and phospho-retinoblastoma protein, but did not regulated cell-cycle proteins in cyclin D1-positive cells." (PMID 25826583, 2015). "We found that PAF1 binds at both typical enhancers and SEs in the multiple myeloma cell line MM1.S, for example, at the CCND2 locus, suggesting it may also have a functional role at enhancers in this disease context." (PMID 37626123, 2023). "ChIP-seq assays showed that acetylation of H3K27 at cell cycle/mitochondrial gene promoters and super-enhancers of genes relevant for multiple myeloma biology (c-MYC, BCL-XL, CCND2, IRF4, MCL1, PIM1, PRDM1, and XBP1) was mildly increased in HDAC3 knockdown cells compared with nonsilencing cells." (PMID 36846090, 2022). "This heterogeneity converges, in most cases, to a functionally dichotomous, mutually exclusive overexpression of the cell cycle regulators CCND1 and CCND2 to which myeloma PC remain addicted, irrespective of primary or secondary genetic events." (PMID 34521827, 2021). "To identify other TF potentially regulating CCND2 enhancer activity in CCND2-expressing HD MM (which lack expression of MAF), we performed differential footprinting analysis in CCND2high vs CCND2low HD myeloma PC." (PMID 34521827, 2021). "Distinct myeloma transcriptome profiles are primarily driven by myeloma initiating events (MIE) and converge into a mutually exclusive overexpression of the CCND1 and CCND2 oncogenes." (PMID 34521827, 2021). "Half of the groups, namely the 11q13, 6p21, 4p16 and Maf group are based on the recurrent translocations in myeloma, while the remaining half is based on the increased expression of cyclin D1 and/or cyclin D2 (D1, D1+D2, D2 and none group)." (PMID 29163849, 2017). "The candidate enhancers of HGF and UCHL1 exemplify de novo formed enhancers, i.e., not present at any stage of late B lineage development, while the CCND2 enhancer provides an example of ‘re-commissioned’ super-enhancer, i.e., active in myeloma but not in normal PC." (PMID 34521827, 2021). "Of note, CCND2 myeloma cells overexpress CDK6 and CDK4 while CCND1 myeloma cells overexpress CDK4 but not CDK6, suggesting that CDK4 is “empty” of cyclin D in CCND2 myeloma cells." (PMID 30545397, 2018).
ovarian carcinoma (29 papers, 2012 to 2025). A malignant neoplasm originating from the surface ovarian epithelium. "Recent related work declared CCND2 inherited genetic variations linked with the risk of colorectal cancer and ovarian cancer." (PMID 24743557, 2014). "Using our ovarian cancer sample, we verified that miR-93-5p is negatively correlated with CCND2 mRNA and protein levels." (PMID 35306579, 2022). "Transfection miR-93-5p mimics to ovarian cancer cells can downregulate the CCND2 gene expression and its protein levels." (PMID 35306579, 2022). "We found that the expression of CCND2 in epithelial ovarian cancer tissue and epithelial ovarian cancer cell A2780 was higher than that of normal ovarian tissue and normal epithelial ovarian cancer cell IOSE80, respectively." (PMID 35306579, 2022). "The two cancer promoters, respectively CCND1 and CCND2, were overexpressed in the ovarian cancer samples, their expression is directly correlated with the upregulated level of HOTAIR." (PMID 34207450, 2021). "CCND2 was previously predicted and confirmed to be a direct target gene of miR−206 in ovarian cancer cells." (PMID 34746018, 2021). "In ovarian cancer cells, HOTAIR positively stimulates CCND1 and CCND2 genes, whose upregulation is associated with tumor progression." (PMID 33540611, 2021). "This activity is related to the negative modulation of miR-206 expression, and the ceRNA regulatory network HOTAIR-miR-206-CCND1/CCND2 contributes to the promotion of ovarian cancer cell proliferation, cell cycle progression, migration, and invasion." (PMID 33540611, 2021). "HOTAIR modulates CCND1 and CCND2 expression through regulating miR-206 expression in ovarian cancer." (PMID 34592939, 2021). "Our immunoblot analysis revealed that cyclin D2 was elevated in UGDH knockdown ovarian cancer cells." (PMID 32893977, 2020). "In ovarian cancer cells, CCND2 has been proven to be a target of miR-145, and the recovery of this gene partially reverses the effect of miR-145." (PMID 33005182, 2020). "CCND2 is frequently silenced in a variety of human cancers, including breast and ovarian cancers, through promoter hypermethylation." (PMID 24586797, 2014). "Also, a higher expression of CCND2 is reported to induce proliferative, migratory and invasive behaviour in human ovarian cancer cells." (PMID 39342193, 2024). "Additionally, miR-206 targets CCND1 and CCND2, inhibiting the proliferation, progression, migration, and invasion of ovarian cancer cells." (PMID 38793064, 2024). "Finally, the upregulation of CCND2 in platinum-resistant PDOs suggests the involvement of cyclins and cyclin-dependent kinases as principal regulators of platinum resistance in ovarian cancer." (PMID 37686015, 2023). "Our research certified that miR-93-5p reduces ovarian cancer malignancy by targeting CCND2." (PMID 35306579, 2022). "Although CCND2 function are well-known, the mechanism of CCND2 expression, degradation in ovarian cancer remains unclear." (PMID 35306579, 2022). "Our results identified that miR-93-5p inhibit ovarian cancer malignancy by regulating CCND2." (PMID 35306579, 2022). "Finally, we confirmed that miR-93-5p and CCND2 expression is negatively correlated in tumor tissues of patients with ovarian cancer." (PMID 35306579, 2022). "Interestingly, transfection of miR-93-5p mimic into ovarian cancer cell can negatively regulate the expression of CCND2 mRNA and protein level." (PMID 35306579, 2022). "Interestingly, a previous study detected a negative regulation relationship between miR-206 and CCND2 in ovarian cancer." (PMID 34746018, 2021). "The following researches confirmed that HOTAIR negatively regulated miR-206 to activate STS2 33 to promote cancer invasion of head and neck squamous cell carcinoma as well as to activate CCND1 and CCND2 34 to stimulate the proliferation, and invasion of ovarian cancer cells." (PMID 32489462, 2020). "HOTAIR regulates CCND1 and CCND2 expression by sponging miR-206 in ovarian cancer." (PMID 32349783, 2020).
ovarian carcinoma (continued). "Accordingly, it is possible that the efficacy of inhibitors such as ribociclib (targeting CDK4/6, the activated binding partner of CCND2) may be underestimated in ovarian cancer PDX models with down-regulated CCND2 expression." (PMID 31004097, 2019). "The same study revealed that SC144 inhibited STAT3 phosphorylation and subsequent expression of survivin, Cyclin-D2 and MMP-7 in a human ovarian cancer cell line." (PMID 36672405, 2023). "We detected CCND2 in ovarian cancer cell A2780 and immortal ovarian epithelial cell IOSE8 and we found CCND2 in A2780 cell is higher than in IOSE8." (PMID 35306579, 2022). "Using real-time PCR, we found that silencing SMYD3 significantly decreased the mRNA levels of CCNA2, CCNB2, CCND2, CDK1 and CDK2 (p<0.05) but increased the mRNA levels of WEE1 (p<0.05), suggesting an essential role for SMYD3 in ovarian carcinoma proliferation." (PMID 31417652, 2019). "More recently, the protective role exerted by two miRNAs, miR-145 and miR-93-5p, in suppressing ovarian cancer cell proliferation and migration through a negative transcriptional regulation of the proto-oncogene CCND2 have been described in two different studies." (PMID 36340025, 2022). "Interestingly, although CCND2 and CCND3 are not overexpressed in human ovarian cancer, messenger RNA expression levels for both CCND2 and CCND3 were significantly upregulated in cancerous ovaries of laying hens." (PMID 23236518, 2012).